USP6 (ubiquitin specific peptidase 6)
Description:
Deubiquitinase with an ATP-independent isopeptidase activity, cleaving at the C-terminus of the ubiquitin moiety. Catalyzes its own deubiquitination. In vitro, isoform 2, but not isoform 3, shows deubiquitinating activity. Promotes plasma membrane localization of ARF6 and selectively regulates ARF6-dependent endocytic protein trafficking. Is able to initiate tumorigenesis by inducing the production of matrix metalloproteinases following NF-kappa-B activation. May act as a GTPase-activating protein for RAB3A.
Synonyms: HRP1; TRE2; Tre-2; TRE17; TRESMCR; USP6-short
Tractability: Antibody: UniProt places it where antibodies can reach, with high confidence; its Gene Ontology location is reachable by antibodies, with high confidence. PROTAC: UniProt records ubiquitination sites on it; ubiquitination databases record sites on it.
Target class: Cysteine protease; Cysteine protease CA clan; Protease; Enzyme; Cysteine protease C19 family
Gene: Protein-coding gene on chromosome 17 (5,116,032 to 5,175,034, forward strand). Ensembl gene ENSG00000129204.
Subcellular location: Cell membrane; Cytoplasm; Endosome
Subcellular location (Human Protein Atlas): Vesicles
Gene Ontology:
Molecular function: cysteine-type deubiquitinase activity; protein binding; cysteine-type endopeptidase activity; nucleic acid binding
Biological process: protein deubiquitination; regulation of postsynaptic neurotransmitter receptor internalization; regulation of vesicle-mediated transport; protein modification process
Cellular component: cytoplasm; glutamatergic synapse; plasma membrane; postsynaptic density, intracellular component; recycling endosome; Golgi apparatus; lysosome; endosome; membrane
Genetic constraint (gnomAD): Loss-of-function variants: 118 observed, 161.22 expected, observed/expected ratio (o/e) 0.73, 90% interval 0.63 to 0.85. The upper end of that interval is the gene's LOEUF score, 0.85, which puts it in group 3 of 6, group 1 being the genes least tolerant of losing a copy. Missense variants: 1,402 observed, 1,659.7 expected, observed/expected ratio (o/e) 0.84, 90% interval 0.81 to 0.88. Synonymous variants: 530 observed, 593.94 expected, observed/expected ratio (o/e) 0.89, 90% interval 0.83 to 0.96.
Homologues: Orthologues: chimpanzee USP6 (96% identical), macaque USP32 (69% identical), dog USP32 (68% identical), mouse Usp32 (67% identical), rat Usp32 (66% identical), tropical clawed frog usp32 (59% identical), zebrafish usp32 (54% identical). Paralogues in human: USP32 (69% identical), USP15 (16% identical), USP4 (16% identical), USP11 (15% identical), USP19 (15% identical), USP24 (13% identical), USP43 (13% identical), USP31 (13% identical), USP9X (12% identical), USP9Y (11% identical), USP8 (11% identical), USP2 (10% identical), and 59 more.
Diseases named in the same sentence as USP6 in open-access papers:
USP6 is named in the same sentence as 70 diseases in open-access papers, as found by Europe PMC text mining. Sharing a sentence is not in itself a finding about the gene and the disease. The quoted sentences say what the papers report.
nodular fasciitis (32 papers, 2014 to 2026). A self-limiting, rapidly growing, non-encapsulated benign neoplasm that arises from the soft tissues. "Nodular fasciitis, a benign, self‐limiting tumor associated with USP6 rearrangement, commonly affects the upper extremities and typically resolves spontaneously." (PMID 41262926, 2025). "Nodular fasciitis is a self-limited process associated with USP6 gene rearrangements while desmoid fibromatosis is a more aggressive and infiltrative process associated with CTNNB1 mutations." (PMID 39436475, 2024). "In a recent report, USP6 rearrangement was found not only in ABCs but also in nodular fasciitis, myositis ossificans, and fibroma of the tendon sheath in soft tissue tumors, which are considered USP6-associated neoplasms." (PMID 39850815, 2024). "USP6 rearrangements in nodular fasciitis play a key role in the differential diagnostic process." (PMID 37735390, 2023). "In nodular fasciitis, chromosomal translocations cause overexpression of USP6, which activates the Wnt/β-catenin pathway.To further determine the role of Wnt signaling in USP6-mediated tumor growth, they tested USP6/NIH 3T3 cells with DKK1, a secreted protein that inhibits Fzd receptor activation." (PMID 40348771, 2025). "Fluorescence in situ hybridization confirmed USP6 gene rearrangement, establishing the diagnosis of nodular fasciitis." (PMID 42029469, 2026). "Between 74 and 100% of nodular fasciitis cases at any anatomic location have been documented to have USP6 gene rearrangements (A)." (PMID 40348771, 2025). "Understanding the fundamental biology of cranial fasciitis is aided by the discovery of USP6 promoter-swapping rearrangements, which also strengthen the biological connection between the condition and nodular fasciitis." (PMID 40348771, 2025). "Recent molecular studies identified USP6 gene fusion in some subtypes, suggesting a clonal neoplasm similar to nodular fasciitis." (PMID 41573443, 2025). "In nodular fasciitis (NF), recurrent USP6 rearrangement and the most frequent fusion partner, MYH9, were identified." (PMID 40348771, 2025). "Among these, USP6 has emerged as a critical regulator in the pathogenesis of diverse malignancies, including pancreatic cancer, aneurysmal bone cysts, breast cancer, nodular fasciitis, cranial fasciitis, colon cancer, and colorectal cancer." (PMID 40348771, 2025). "Following the identification of USP6 fusions in nodular fasciitis in 2011, 16 cases involving the breast or axilla have been documented, with TRAF6, c-jun, and collagen 1 being the targets." (PMID 40348771, 2025). "The interaction between USP6 and c-Jun contributes to the development of various tumors, including benign mesenchymal neoplasms like nodular fasciitis and aneurysmal bone cysts." (PMID 40348771, 2025). "It is noteworthy that both reports were published prior to the discovery of USP6 being rearranged recurrently in nodular fasciitis." (PMID 41020205, 2025). "It is of interest that USP6 rearrangements have been described in several benign fibroblastic/myofibroblastic tumors, such as nodular fasciitis, cellular fibroma of tendon sheath, myositis ossificans, and fibro-osseous pseudotumor of digits." (PMID 38792018, 2024). "In the literature there are two cases reported with a PPP6R3::USP6 fusion and typical morphology of a nodular fasciitis but with a malignant transformation." (PMID 37951844, 2024). "USP6 fusions are regularly found in tumors with mesenchymal origin that can show bone metaplasia, such as nodular fasciitis, myositis ossificans, fibro-osseous pseudo-tumor of digits and aneurysmal bone cysts." (PMID 37951844, 2024). "As a ubiquitin-specific protease, USP6 is overexpressed in benign tumors, such as nodular fasciitis and aneurysmal bone cyst." (PMID 35091542, 2022).
nodular fasciitis (continued). "Recently, studies have identified a rearrangement of the ubiquitin-specific protease 6 (USP6) gene as a recurrent and specific finding leading to the increased acceptance that nodular fasciitis represents a clonal neoplastic proliferation." (PMID 31377545, 2019). "Aneurismal bone cyst and nodular fasciitis are characterized by structurally similar USP6 fusion genes." (PMID 26198694, 2015). "Recently, Oliveira and Chou suggested that aneurismal bone cysts and nodular fasciitis reside in the same biologic spectrum as USP6-induced tumors." (PMID 26198694, 2015). "It is noteworthy that USP6 rearrangements have also been detected in close to 90 % of nodular fasciitis, a soft tissue tumor, often a reaction to trauma, that resolves spontaneously." (PMID 25409853, 2014). "ABCs are described as benign lesions as the USP6 gene has been described in other benign entities, including nodular fasciitis, myositis ossificans, fibro-osseous pseudotumor of digits, and fibroma of the tendon sheath, all sharing histopathological findings with ABC." (PMID 40822658, 2025). "Ubiquitin-specific protease 6 (USP6) rearrangements have been identified as a consistent marker in nodular fasciitis, confirmed by fluorescence in situ hybridization (FISH), and may offer diagnostic assistance in differentiating fasciitis ossificans as well." (PMID 38594664, 2024). "There was also a report that RT-PCR of cytology specimens could be used to confirm USP6 gene rearrangement, and if nodular fasciitis could be diagnosed, follow-up observation could be an option." (PMID 39816285, 2024). "The identification of structurally similar USP6 fusion genes in both the aneurismal bone cyst and nodular fasciitis suggested that these are clonal neoplastic disorders that may belong to the same biologic spectrum." (PMID 26198694, 2015). "This gradual disappearance of the USP6 split-signals harboring neoplastic cells suggests that apoptosis and/or senescence might be involved in NF as the mechanism of the self-limited nature of nodular fasciitis." (PMID 34381187, 2021). "Recently, RT-PCR and other methods have shown that USP6 gene rearrangement is detected in up to 90% of cases, and MYH9 is identified in approximately 70% of cases, making it useful for the diagnosis of nodular fasciitis." (PMID 39816285, 2024). "recognized recurrent USP6 rearrangement and the most common fusion partner MYH9 in nodular fasciitis (NF)." (PMID 36727055, 2022). "Certain tumor types, such as NTRK-rearranged spindle cell neoplasm and nodular fasciitis, are known to exhibit fusions with multiple fusion partners for invariable partner genes such as NTRK1/2/3 and USP6." (PMID 32825119, 2020). "USP6 testing is negative in 10 to 14% of nodular fasciitis cases, so FISH testing is not a sensitive enough test to exclude the diagnosis of nodular fasciitis." (PMID 28018683, 2016). "USP6 FISH testing was negative in our patient which raises the possibility of nodular fasciitis-like granulation tissue as an alternative diagnosis." (PMID 28018683, 2016). "It is noteworthy that whereas MYH9, on chromosome 22q12.3, is the common fusion partner (65 % of cases) with USP6 in nodular fasciitis, it has not been reported in ABC." (PMID 25409853, 2014). "Notably, we believed that FO may demonstrate more similar clinicopathologic and genetic manifestations with MO/FOPD and ST-ABC instead of nodular fasciitis for involving lower limbs most frequently and showing recurrent COL1A1::USP6 fusion." (PMID 36727055, 2022).
aneurysmal bone cyst (19 papers, 2008 to 2025). A locally aggressive and destructive benign cystic lesion of the bone. "Recurrent USP6 rearrangement was discovered by Oliveira and colleagues in 2004 in primary aneurysmal bone cysts (ABCs) (63%)." (PMID 40348771, 2025). "In 2004, Oliveira and colleagues found recurrent USP6 rearrangement in primary aneurysmal bone cysts (ABCs) (63%)." (PMID 36727055, 2022). "Intra-articular nodular fasciitis and aneurysmal bone cyst seem to belong to the same biological spectrum defined as USP6-induced tumors according to the report." (PMID 31163331, 2019). "UBP6 (encoded by USP6/TRE-17), the first DUB to be identified as an oncogene, has in recent years been directly linked to human cancers, primarily aneurysmal bone cysts (ABCs), which are locally aggressive bone tumors." (PMID 19007433, 2008). "USP6, also known as TRE17, has been studied primarily in aneurysmal bone cysts." (PMID 36883930, 2023). "Likewise MDM2 amplifications for the diagnosis of low-grade osteosarcoma, HEY1 fusions in case of mesenchymal chondrosarcoma and USP6 fusions in aneurysmal bone cyst." (PMID 31838586, 2020). "The initial description of USP6 rearrangement was published more than 15 years ago in an aneurysmal bone cyst (ABC), which is thought to be a benign bone tumor." (PMID 40348771, 2025). "Given the radiologic differential diagnosis of an aneurysmal bone cyst (ABC), USP6 FISH was performed which was inconclusive." (PMID 31049020, 2019). "The USP6 gene rearrangement identified in our case is a further support to this speculation and the common pathogenesis as USP6 gene rearrangement has been documented to be present in most cases of primary aneurysmal bone cyst." (PMID 31319877, 2019). "The mononuclear nuclei exhibit one fused red/green signal corresponding to a normal 17p USP6 locus (black arrow) and a pair of split green and red signals (white arrows) indicating a rearrangement of the USP6 locus consistent with the diagnosis of aneurysmal bone cyst." (PMID 24438319, 2014). "Aneurysmal bone cyst (ABC), once considered a reactive lesion, has been proven to be a neoplasia characterized by rearrangements of the USP6-gene." (PMID 24438319, 2014). "Aneurysmal bone cysts (ABC) are a benign, clonal neoplasm involving translocations of the USP6 gene, a ubiquitin-specific protease involved in a variety of processes including protein stability and degradation, cell signaling, angiogenesis, and inflammation." (PMID 37522932, 2023). "Our first impression of the case was aneurysmal bone cyst although FISH detected no USP6 split signal in the tumor cells." (PMID 36320082, 2022). "In total, through Archer FusionPlex, fluorescence in situ hybridization and/or reverse transcriptase-polymerase chain reaction the EWSR1-NFATC2 rearrangement was identified in 6 of 9 SBC, 3 of 12 benign vascular tumors, and none of 5 aneurysmal bone cyst lacking USP6 fusion." (PMID 34081036, 2021). "Among those tumors with consistent USP6 rearrangement, some arise from soft tissue and show bone metaplasia, including myositis ossificans (MO), fibro-osseous pseudotumor of digits (FOPD), soft tissue aneurysmal bone cyst (ST-ABC) and fasciitis ossificans (FO)." (PMID 36727055, 2022).
Ewing sarcoma (10 papers, 2015 to 2025). A small round cell tumor that lacks morphologic, immunohistochemical, and electron microscopic evidence of neuroectodermal differentiation. "dox-inducible expression of USP6 in the A673 patient-derived Ewing sarcoma cell line caused a significant delay in the time required for tumors to reach terminal volume." (PMID 37615015, 2023). "It is tempting to speculate that USP6’s ability to induce systemic immune activation and an abscopal response underlies the association of high USP6 expression with significantly improved overall survival of patients with Ewing sarcoma." (PMID 37615015, 2023). "USP6 expression in Ewing sarcoma cells directly stimulates NK cell activation and degranulation in vitro, and functions by increasing surface levels of multiple NK cell-activating ligands." (PMID 37615015, 2023). "Expression of USP6 in Ewing sarcoma cells directly induces NK cell activation by driving surface upregulation of NK-activating ligands." (PMID 37615015, 2023). "Our results similarly point to a pivotal role for NK cells in Ewing sarcoma tumor growth, with depletion of NK cells completely abolishing the tumor-suppressive effects of USP6." (PMID 37615015, 2023). "Here we report that natural killer (NK) cells are essential for its tumor-inhibitory functions, as NK cell depletion reverses USP6-mediated suppression of Ewing sarcoma xenograft growth." (PMID 37615015, 2023). "In the current study, we demonstrate that NK cells are required for inhibition of Ewing sarcoma xenograft growth by USP6." (PMID 37615015, 2023). "We previously reported that USP6 induces intratumoral infiltration and activation of multiple innate immune lineages in Ewing sarcoma xenografts in nude mice." (PMID 37615015, 2023). "Validated LAKs were cocultured at various effector:target (E:T) ratios with two independent Ewing sarcoma cell lines expressing USP6 in a dox-inducible manner, USP6/A673 and USP6/RD-ES." (PMID 37615015, 2023). "In sum, these results identify USP6 as the first Ewing sarcoma–intrinsic factor capable of directly activating antitumorigenic immunity, both intratumorally and systemically." (PMID 37615015, 2023). "In sum, these results indicate that USP6 is sufficient to drive intratumoral activation of NK cells in Ewing sarcoma in vivo, and that NK cells are required for suppression of tumor growth by USP6." (PMID 37615015, 2023). "We recently reported an unexpected tumor-suppressive role for the deubiquitinating enzyme ubiquitin-specific protease 6 (USP6) in Ewing sarcoma." (PMID 37615015, 2023). "Our study provides further insight into the mechanism by which USP6 modulates the immune TME in Ewing sarcoma to suppress tumorigenesis." (PMID 37615015, 2023). "USP6 directly activates NK cell cytolytic function, inducing both intratumoral and systemic activation of NK cells in an Ewing sarcoma xenograft model." (PMID 37615015, 2023). "Remarkably, USP6 expression in subcutaneous Ewing sarcoma xenografts induces systemic activation of NK cells in peripheral blood (PB) and also triggers an abscopal response against distal subcutaneous tumors." (PMID 37615015, 2023). "Together, these results reveal that intratumoral expression of USP6 in Ewing sarcoma has broad effects on systemic innate immune activity." (PMID 37615015, 2023). "We demonstrate that USP6-mediated suppression of Ewing sarcoma tumorigenesis is dependent on NK cells." (PMID 37615015, 2023). "We recently reported that ubiquitin-specific protease 6 (USP6) functions as a tumor suppressor in Ewing sarcoma, and identified it as the first cell-intrinsic factor to modulate the Ewing sarcoma immune tumor microenvironment (TME)." (PMID 37615015, 2023). "Together, these results indicate that USP6 expression in Ewing sarcoma cells directly activates NK cells by enhancing both immune synapse formation (via ICAM-1) as well as degranulation via multiple NK cell-activating ligands." (PMID 37615015, 2023).